GDNF (glial cell derived neurotrophic factor)
Diseases named in the same sentence as GDNF in open-access papers (continued):
Sharing a sentence is not in itself a finding about the gene and the disease.
glioma (continued). "SPIONs drive miR-485-5p overexpression in cells and inhibit endogenous Tie1 expression to downregulate the protein expression levels of Fgf2/GDNF/GFAP/BDNF and significantly weaken the in vivo and in vitro viability of gliomas." (PMID 32174801, 2020). "Glial-derived neurotrophic factor (GDNF) has been identified as a potent neurotrophic factor in a variety of neuronal cell populations and is overexpressed in human gliomas." (PMID 33511267, 2020). "To investigate the mechanism of crosstalk between DNA methylation and histone acetylation in regulating high GDNF transcription in GBM cells, we examined expression of the proto-oncogene CREB in different grades of glioma tissues and GBM cell lines." (PMID 32183903, 2020). "Another ceRNA GDNF, a member of TGF-β super-family, has been revealed to strongly induce glioma cell proliferation and migration." (PMID 31719831, 2019). "Glioma cells release chemo-attractans, such as monocyte chemo-attractant protein-1 (MCP-1), fractalkine (CX3CL1), glial cell–derived neurotrophic factor (GDNF), and colony stimulating factor-1 (CSF)-1) that recruit GAMs to tumor tissue." (PMID 31467533, 2019). "Glial cell line-derived neurotrophic factor (GDNF), originally isolated from a rat glioma cell line, is a neurotrophic factor with potent effects on dopaminergic, serotonergic, noradrenergic and cholinergic neurons." (PMID 29785638, 2018). "GDNF is not only identified as an important factor in macrophage infiltration into GBM, contributing to GBM progression, but also it can promote glioma cell invasion through its receptors that are present on invasive GBM cells." (PMID 28198665, 2017). "Next, to ascertain if GDNF promoted proliferation of C6 glioma cells through NRP1, we performed knockdown of rat NRP1 using the lentivector shRNA transduction of C6 glioma cells." (PMID 29088765, 2017). "Next, the effects of Egr-1 overexpression on Egr-1 binding to GDNF promoter II, RNA POL II recruitment, and GDNF transcription in C6 glioma cells were determined by gene overexpression, ChIP, and real-time PCR." (PMID 28187447, 2017). "In conclusion, we found that H3K9 acetylation in the Egr-1 binding sites of GDNF promoter II, binding of Egr-1 to such sites, RNA POL II recruitment in that region, and Egr-1 expression were significantly increased in high-grade glioma tissue." (PMID 28187447, 2017). "In this study, proN-cadherin altered the adhesion properties of U251 glioma cells, and it mediated GDNF-induced cell motion, presumably because it enhanced heterophilic adhesion between the ECM and U251 glioma cells and accelerated cell activation." (PMID 28212546, 2017). "Knock-down of GDNF and its binding receptor, GDNF family receptor alpha 1 (GFRA1) decreases the proliferation of C6 glioma cells." (PMID 29088765, 2017). "Glial cell line-derived neurotrophic factor (GDNF), a member of the GDNF family of ligands (GFL), is strongly expressed in human gliomas." (PMID 29088765, 2017). "In this study, H3K9 acetylation in Egr-1 binding sites of GDNF promoter II, Egr-1 binding, and RNA POL II recruitment in that region were significantly increased in high-grade glioma tissue." (PMID 28187447, 2017). "bFGF promotes GDNF expression accompanied with the activation of ERK5, ERK1/2 and their downstream transcription factors (c-fos, EGR1) in C6 glioma cells and results in C6 glioma cells proliferation." (PMID 29246166, 2017). "We inserted the full-length mouse GDNF 3'-UTR into downstream of the luciferase gene in the pGL3-Promoter vector and estimated the luciferase activity in transiently transfected C6 glioma cells." (PMID 22248285, 2012). "An investigation into glioma patients reported a positive correlation between serum soluble α-Klotho (sαKlotho) levels and IL-6 (p = 0.0347), along with other biomarkers such as VEGF, fractalkine, IFN-γ, GDNF, IL-4, and IL-13." (PMID 40426990, 2025).
glioma (continued). "Similarly, histones H3K9 and H3K4 acetylation and DNA methylation have been reported to be involved in GDNF and SOX1 overexpression in gliomas." (PMID 35392088, 2022). "Glial cell line-derived neurotrophic factor (GDNF) promotes glioma development and progression, and TRIM21-mediated cAMP response element-binding protein (CREB) ubiquitination decreases the transcription of GDNF and inhibits glioma genesis and development." (PMID 36159815, 2022). "The possible interaction between TGF-β (GDNF) and SOXB1 (SOX1, SOX2, SOX3) family members might explain the difficulties in regulating glioma stem cell recurrence after surgical tumor resection and drug resistance." (PMID 35392088, 2022). "The fractions were lyophilized and then screened for modulation of neurotrophic (BDNF: brain-derived neurotrophic factor; and GDNF: glial cell-derived neurotrophic factor) and neuroprotective (HSP70: heat shock protein 70) signaling in C6 glioma cells at an initial concentration of 50 μg/mL." (PMID 34299002, 2021). "In vitro migration tests showed that GDNF is a strong chemical attractant of microglia but does not affect glioma-induced astrogliosis." (PMID 33511267, 2020). "Histone hyperacetylation at these sites facilitates high-level GDNF transcription in C6 glioma cells, but the specific mechanism has not yet been elucidated." (PMID 28187447, 2017). "Gliomas help recruit TAMs to the TME by secreting various chemokines, including monocyte chemoattractant proteins (MCP-1/CCL2 and MCP-3), C-X-C motif chemokine 12 (CXCL12), colony-stimulating factor 1 (CSF-1), lysyl oxidase (LOX), and glial cell-derived neurotrophic factor (GDNF)." (PMID 38254796, 2024). "These astrocytes are indirectly involved in glioma spreading, including a metabolic way, by synthetizing multiple cytokines: brain-derived neurotrophic factor (BDNF), transforming growth factor α (TGF-α), sphingosine-1-phosphate, glial cell line-derived neurotrophic factor (GDNF)." (PMID 39539752, 2024). "Some studies have found that overexpression of EGR-1 may participate in the recruitment of RNA pol II to the GDNF promoter in a non-binding manner, and thus is involved in the regulation of GDNF transcription in glioma cells." (PMID 34557404, 2021). "Glial cell line-derived neurotrophic factor (GDNF) is highly expressed in all types of gliomas, regardless of grade or form, and this expression pattern contributes to the recruitment and activation of caner-associated fibroblasts, leading to an inflammatory response." (PMID 34513834, 2021). "It is known that the astrocytes or glioma cells induce and strengthen BBB functions of brain endothelial cells via a range of released factors, including transforming growth factor-β (TGFβ), glial-derived neurotrophic factor (GDNF) and basic fibroblast growth factor (bFGF)." (PMID 29059256, 2017). "In conclusion, highly expressed Egr-1 may be involved in the recruitment of RNA POL II in GDNF promoter II in a non-binding manner, and thereby involved in regulating GDNF transcription in high-grade glioma cells." (PMID 28187447, 2017). "Collectively, these findings indicate that in high-grade glioma cells, highly expressed Egr-1 may be involved in recruiting RNA POL II in GDNF promoter II in a non-binding manner, suggesting that Egr-1 helps regulate high-level GDNF transcription." (PMID 28187447, 2017).
amyotrophic lateral sclerosis (40 papers, 2011 to 2025). Amyotrophic lateral sclerosis (ALS) is a neurodegenerative disease characterized by progressive muscular paralysis reflecting degeneration of motor neurons in the primary motor cortex, corticospinal tracts, brainstem and spinal cord. "Previously, we engineered UCB-MCs transduced with adenoviral vectors encoding VEGF and GDNF for the treatment of amyotrophic lateral sclerosis (ALS) and demonstrated a prominent symptomatic control and prolonged life-time in ALS mice after transplantation." (PMID 27003408, 2016). "Up to now, the first clinical study involving the transplantation of genetically modified cells into human spinal cord, is about amyotrophic lateral sclerosis at 2022, overexpressing glial cell line-derived neurotrophic factor (GDNF)." (PMID 37492521, 2023). "Earlier we have demonstrated that specific gene combinations VEGF+GDNF+NCAM improve functional outcome in amyotrophic lateral sclerosis (ALS) mouse model." (PMID 29180963, 2017). "GDNF supports dopaminergic and motor neuron survival in PD and amyotrophic lateral sclerosis (ALS), while CNTF may promote remyelination and motor/oligodendrocyte viability in ALS and SCI." (PMID 40943142, 2025). "Nevertheless, GDNF appears to have an important role in neuromuscular diseases, such as amyotrophic lateral sclerosis, where in animal models it could prevent the degeneration of motor neurons." (PMID 38519465, 2024). "Moreover, GDNF is largely studied in neuromuscular pathologies, as it can prevent motor neuron degeneration in animal models of amyotrophic lateral sclerosis (ALS) and it represents a possible biomarker to predict ALS development." (PMID 32252363, 2020). "Due to the capability to support motoneurons, GDNF has also been tested for the ability to slow down the progression of amyotrophic lateral sclerosis (ALS), an incurable disease with very poor prognosis and an average survival below five years after the diagnosis." (PMID 32911810, 2020). "GDNF prevented motor neuron degeneration in animal models of amyotrophic lateral sclerosis (ALS), making it a potential biomarker for predicting ALS development." (PMID 39077458, 2024). "A few studies have investigated the anti-inflammatory properties of GDNF in neurodegenerative disease models, such as PD, Alzheimer’s disease (AD), amyotrophic lateral sclerosis (ALS), and multiple sclerosis (MS)." (PMID 34769132, 2021). "GDNF is a diffusible peptide, involved in neuronal differentiation and survival, and has been identified as potential biomarker in AD in an unbiased proteomic assay, in amyotrophic lateral sclerosis and is the most potent dopaminergic factor described for the treatment of PD." (PMID 31456664, 2019). "Similarly, elevated levels of GDNF expression in regenerating muscles fibers in subjects with neuromuscular disease have also been described, as well as continued expression in extraocular muscles from subjects with amyotrophic lateral sclerosis." (PMID 30142211, 2018). "Furthermore, transplantation of human NPCs committed to a glial fate that have been genetically engineered to overexpress GDNF promoted neuronal survival and regeneration in primate models of amyotrophic lateral sclerosis (ALS)." (PMID 33117368, 2020). "The neuroprotective effects of GDNF may be used to develop treatments and therapies to ameliorate neurodegenerative diseases such as amyotrophic lateral sclerosis (ALS)." (PMID 32897420, 2020). "Because of the significant involvement of the GDNF at the NMJ, we highlight here the GDNF/NMJ cross-talk in the context of severe disorders such as Alzheimer’s disease (AD), Amyotrophic Lateral Sclerosis (ALS) and Spinal Muscular Atrophy (SMA)." (PMID 33374485, 2020). "For instance, hind limb muscles of amyotrophic lateral sclerosis mouse models display a significant decline in the number of NMJs expressing BDNF, NT-4, GDNF, p75NTR, TrkB, and TrkC." (PMID 31514753, 2019).
amyotrophic lateral sclerosis (continued). "In PWH, several of the DMRs identified were annotated to genes that are involved in biological pathways of potential importance for HIV or exercise adaptation, including amyotrophic lateral sclerosis signaling (ALS); glutamate receptor signaling; and glial cell‐derived neurotrophic factor (GDNF)." (PMID 37920126, 2024). "BDNF and GDNF have been long described as major regulators of survival, maintenance and regeneration of specific neuronal populations in the adult brain, so as to be considered valuable therapeutic options for various neurodegenerative diseases, including amyotrophic lateral sclerosis (ALS)." (PMID 30210286, 2018). "The receptor tyrosine kinase Ret (c-Ret) transduces the glial cell line-derived neurotrophic factor (GDNF) signal, one of the neurotrophic factors related to the degeneration process or the regeneration activity of motor neurons in amyotrophic lateral sclerosis (ALS)." (PMID 24868525, 2014). "Moreover, released by the muscle in an autocrine fashion after injury is the glial-derived neurotrophic factor GDNF, whose direct muscle delivery with human mesenchymal stem cells improves motor neuron survival and function in an amyotrophic lateral sclerosis (ALS) model." (PMID 32012727, 2020). "For example, GDNF-fragment C promotes neuronal survival and neurite outgrowth in animal models of Parkinson’s disease and amyotrophic lateral sclerosis (ALS), and BDNF-fragment C is protective in a mouse model of ALS, although no synergistic effect of this recombinant molecule was found." (PMID 22837670, 2012).
Alzheimer disease (33 papers, 2011 to 2026). A progressive, neurodegenerative disease characterized by loss of function and death of nerve cells in several areas of the brain leading to loss of cognitive function such as memory and language. "In contrast, GDNF levels were found to be decreased in Alzheimer’s disease (AD), leading to progressive loss of cognitive function and dementia." (PMID 29617307, 2018). "Interestingly, Alzheimer's disease (AD), a condition with pathological loss of basal forebrain cholinergic function and significantly decreased serum GDNF levels, is also associated with a high burden of chronic pain." (PMID 39639706, 2024). "These outcomes accord with the study that supports the hypothesis that GDNF deficiency may lead to such neurodegenerative processes in Alzheimer’s disease: amyloid precursor proteins are retained in the Golgi apparatus due to insufficient GDNF levels." (PMID 39502974, 2024). "We found a cluster of keywords across publications related to Nurr1, Alzheimer's disease pathology, PD, dopaminergic neurons, GDNF, alpha-synuclein, canonical ligand-binding pocket, and cilostazol." (PMID 31772707, 2019). "In what respects glial cell line-derived neurotrophic factor (GDNF) the sparse available studies also indicate its levels are changed in cerebrospinal fluid and serum of patients with early Alzheimer's disease." (PMID 22654714, 2011). "There is mounting evidence that GDNF levels may play a role in the etiology and progression of illness, as they do in Alzheimer's disease with cognitive impairment." (PMID 35360515, 2022). "The remaining open questions are whether APP regulates GDNF expression in different types of neurons within the CNS and whether GDNF participates in Alzheimer’s disease." (PMID 28878618, 2017). "However, there is little published data on the role of GDNF in Alzheimer’s disease." (PMID 36555569, 2022). "In a streptozotocin-induced astrocytotoxicity model for Alzheimer’s disease, memantine ameliorated BDNF and GDNF decline in astrocytes along with phosphorylation of IRS-1, Akt, and GSK-3α/β." (PMID 32782018, 2020). "In Alzheimer’s disease, chronic inflammation in the brain exacerbates the pathological condition and cognitive decline because inflammation is toxic to neurons and suppresses the production of neurotrophic factors such as BDNF, GDNF and NGF." (PMID 25760987, 2015).
schizophrenia (33 papers, 2011 to 2025). A major psychotic disorder characterized by abnormalities in the perception or expression of reality. "There have been numerous attempts to find genetic associations between the GDNF susceptibility locus and schizophrenia with moderate success." (PMID 38674063, 2024). "Despite a number of case–control and genome-wide association studies (GWAS), only two single nucleotide variants and a trinucleotide repeat polymorphism in the GDNF gene were shown to nominally associate with schizophrenia." (PMID 38674063, 2024). "In this study, a schizophrenia-associated SNP affecting a microRNA binding site in the 3′-UTR of the GDNF gene has been functionally characterized." (PMID 38674063, 2024). "There is indirect evidence for such a link: particularly, application of drugs that cause schizophrenia-like symptoms elevates GDNF expression." (PMID 38646100, 2024). "The first comprehensive genetic association analysis investigated a set of nine single nucleotide polymorphisms (SNPs) spanning the entire 40 kb of the GDNF locus in a large schizophrenia cohort." (PMID 38674063, 2024). "In this case–control study we found that the rs11111 SNP in the 3′-UTR of the GDNF gene is statistically associated with schizophrenia susceptibility in general and with its positive and cognitive symptoms in particular." (PMID 38674063, 2024). "Based on this background, the aim of the present study was to seek genetic associations between non-coding SNPs in the GDNF gene and schizophrenia." (PMID 38674063, 2024). "As dysfunctional dopamine signaling is a hallmark of schizophrenia, several studies have addressed the involvement of dopaminergic neurons in general and GDNF in particular in schizophrenia." (PMID 38674063, 2024). "Apart from plasma or brain GDNF levels per se, impaired GDNF signaling has also been implicated in the pathogenesis of schizophrenia." (PMID 38674063, 2024). "GDNF has been implicated in several cerebellar-related neurodevelopmental disorders including schizophrenia and ADHD." (PMID 37251644, 2023). "As a group, FEP patients displayed higher CSF GDNF levels than HCs, demonstrating that, overall, higher GDNF levels are associated with schizophrenia." (PMID 35618883, 2022). "In one recent study, GDNF levels were found to be associated with working memory in healthy controls and attention deficit in schizophrenia patients." (PMID 34763683, 2021). "Recent findings from Ahmadiantehrani and Ron seem to corroborate these results by revealing that upregulated DRD2 signaling, a hallmark of schizophrenia, resulted in elevated GDNF expression levels." (PMID 24324616, 2013). "Therefore, video game training is likely to cause an increase in the release of GDNF in patients with schizophrenia, thereby alleviating the abnormal transmission of dopamine in the striatum." (PMID 40251163, 2025). "Addressing these gaps could enhance our understanding of GDNF's role in schizophrenia and improve diagnostic and therapeutic approaches." (PMID 39881227, 2025). "Our results imply that the rs11111 ‘G’ allele occurring more frequently in patients with schizophrenia might downregulate GDNF expression in a miRNA-dependent fashion." (PMID 38674063, 2024). "It seems reasonable to assume that non-coding polymorphisms of the GDNF gene might modulate the risk of schizophrenia by influencing GDNF plasma levels, but the association studies cited above did not investigate this correlation." (PMID 38674063, 2024). "Amphetamine administration elevates the endogenous GDNF expression in the nigrostriatal tract, increases the concentration of dopamine in synapses, and elevates the schizophrenia susceptibility." (PMID 38646100, 2024). "The GDNF gene is localized in the 5p12—p13.1 locus associated with schizophrenia." (PMID 38646100, 2024).